RNU6-9 (RNA, U6 small nuclear 9)
Synonyms: U6-9; RP106
Gene: Small nuclear RNA gene on chromosome 19 (893,484 to 893,590, forward strand). Ensembl gene ENSG00000207507.
Gene Ontology:
Molecular function: U4 snRNA binding
Biological process: formation of quadruple SL/U4/U5/U6 snRNP; spliceosomal tri-snRNP complex assembly
Cellular component: U4/U6 x U5 tri-snRNP complex; U6 snRNP
Homologues: Orthologues: chimpanzee U6 (100% identical), dog U6 (100% identical), guinea pig U6 (100% identical), macaque U6 (100% identical), mouse Gm22246 (100% identical), pig U6 (100% identical), rat U6 (100% identical). Paralogues in human: RNU6-1 (100% identical), RNU6-2 (100% identical), RNU6-3P (100% identical), RNU6-4P (100% identical), RNU6-5P (100% identical), RNU6-6P (100% identical), RNU6-12P (99% identical), RNU6-13P (99% identical), RNU6-17P (99% identical), RNU6-18P (99% identical), RNU6-25P (99% identical), RNU6-32P (99% identical), and 1288 more.